TNF (tumor necrosis factor)
Diseases named in the same sentence as TNF in open-access papers (continued):
Sharing a sentence is not in itself a finding about the gene and the disease.
cancer (continued). "Pro-inflammatory macrophages can kill cancer cells directly, via mechanisms dependent on reactive oxygen species (ROS), reactive nitrogen species, and IL-1β and TNF-α production, or indirectly, through the activation of other immune cells, like cytotoxic T cells and NK cells." (PMID 37686663, 2023). "Thus, cancer-derived inflammatory cytokines, such as IL-11, TGFβ, and TNFα, can stimulate the reversion of mature adipocyte phenotypes." (PMID 36672449, 2023). "Surprisingly, HDGF and TNFα decreased the cell viability of the cancer organoids." (PMID 37047540, 2023). "Moreover, induction of immunogenic apoptosis or necroptosis after treatment of cancer cells with IAP inhibitors in combination with TNF-α or radiation opens up new avenues in cancer therapy." (PMID 36845731, 2023). "AXIN2 overexpression under hypoxic conditions was shown to exhibit an opposite effect to miR-1275 overexpression, i.e. AXIN2 overexpression was able to inhibit perforin, IFN-γ and TNF-α secreted by NK-92 cells after incubated with Panc-1 and inhibited the ability of NK-92 cells to kill cancer cells." (PMID 38035113, 2023). "The functional potential of the T-cell anti-cancer response was then assessed according to the production of IFN-γ, TNF-α, perforin, and Granzyme B. Our findings indicated that PD-L1 blockade by pentamidine enhanced the cytotoxic potential of T cells in all tested cancer cell lines." (PMID 37205112, 2023). "However, no consensus has been established regarding the actual effects of anti-TNFα mAb on malignant tumors." (PMID 36996146, 2023). "The results of this study support these findings, as the secretion of TNF-α and expression of M1 macrophages were reduced in cocultures treated with melatonin; this hormone could be a potential therapeutic strategy for cancer." (PMID 37569777, 2023). "Dietary vitamin K (phylloquinone) consumption has been known to have an inhibitory effect on systematic inflammation by reducing the level of proinflammatory cytokines, including tumor necrosis factor-α and interleukin-6,41 a well-known factor for driving the initiation and development of cancer." (PMID 35871570, 2023). "TNF-α is involved in a variety of regulatory processes in normal and cancer cells." (PMID 37736898, 2023). "Moreover, monocytes activated by cancer-derived-EVs increased HLA-DR expression, reactive oxygen intermediate production, accumulation of mRNA and secretion of TNF, IL-10, IL-12p409." (PMID 37173330, 2023). "Also, the immune checkpoint VSIR was expressed on some T cell subpopulations of MBC samples and interacted with the cancer cells via TNF." (PMID 37696831, 2023). "Furthermore, taxanes, including paclitaxel, induced an increase in IL-1β, IL-6, and TNF-α levels in patients with cancer." (PMID 37275575, 2023). "Thus, inhibition of specific proteasomal deubiquitinases deregulated in HNSCC warrants further investigation as a novel therapeutic avenue to sensitize these cancers to TNFα- and radiation-induced cytotoxicity." (PMID 37055579, 2023). "TNFα is a key cytokine involved in the generation of the proinflammatory response and many different cellular responses, such as the up-regulation of anti-apoptotic genes, inducing cell survival and proliferation, but also cancer invasion." (PMID 36835413, 2023). "The inflammatory markers interleukin 6 (IL‐6) and tumor necrosis factor alpha (TNFα) were included as inflammation may play a role in cancer recurrence and mortality." (PMID 37269192, 2023).
cancer (continued). "Therefore, this review summarizes the current knowledge of the implications of anesthesia on cancers from the insights of TNF-α release and provides future anesthetic strategies for improving oncological survival." (PMID 36765695, 2023). "TNF-α-induced NF-κB nuclear translocation has been known to activate the downstream anti-apoptotic genes/proliferation genes to promote cancer cell survival and growth in various human cancers." (PMID 38037106, 2023). "In addition, by inhibiting p21/WAF1 induction, MAP17 can prevent tumor necrosis factor (TNF)-induced G1 arrest in cancer cells." (PMID 36737832, 2023). "Moreover, based on the results of KEGG pathway analysis, the PI3K–AKT, IL-17, and TNF signaling pathways were identified as the important cancer-related pathways of PD anti-GC." (PMID 37361599, 2023). "Thus, understanding the role of M. hyorhinis-induced TNF-α in establishing the link between inflammation and cancer has the potential to support the development of an effective strategy for PCa therapy." (PMID 37867861, 2023). "Our results indicate that endogenous R-RAS2Q72L, but not wild-type R-RAS2, is also required for the proper engagement of a wide variety of general immune and inflammatory responses in cancer cells (TNFα, NFκB, IFN) that likely impact in both the innate and adaptive immune system cells." (PMID 36476833, 2023). "TNF-α and its receptors exert biological functions in cancer cells by activating distinct signaling pathways, including NF-κB and c-Jun N-terminal kinase (JNK), in which NF-κB is an anti-apoptotic signal while sustained JNK activation contributes to cell death." (PMID 36765695, 2023). "Additionally, TNF-α and IFN-γ also contribute to cancer cachexia-associated adipocyte wasting through reduction in glucose uptake and promoting insulin resistance." (PMID 37998333, 2023). "Upon dysregulation, TNF-α mediates a wide variety of diseases, including cancer." (PMID 36903437, 2023). "Among the immunological mechanisms of defense against cancer, an important role is assigned to the activity of cytokines, belonging to many groups, including: interleukins, interferons, chemokines, and the tumor necrosis factor (TNF) superfamily." (PMID 38001676, 2023). "TNF-α plays different roles in the pre-cancerous and cancer microenvironments." (PMID 36674931, 2023). "However, direct targeting of this pathway is associated with significant toxicity; thus, it is vital to identify novel mechanism(s) contributing to NFκB activation and TNFα resistance in cancer cells." (PMID 37055579, 2023). "Human cross-sectional studies support that regular moderate physical exercise releases anti-inflammatory cytokines and reduces the production of pro-inflammatory cytokines or cancer biomarkers, such as tumor necrosis factor-alpha (TNFα), interleukin-6 (IL-6), and C-reactive protein (CRP)." (PMID 36765772, 2023). "Our model accurately identified genes regulated by NFκB in response to TNF in cancer patients." (PMID 37475016, 2023). "TNFα is known to promote cancer cell proliferation, which we could observe in our experiments with LoVo cells." (PMID 36900285, 2023). "Cancer cells can release procoagulant factors such as tissue factor and thrombin, and there is often inflammation leading to the recruitment of proinflammatory cytokines such as tumor necrosis factor-α (TNF-α) and interleukin-1 (IL-1)." (PMID 37213972, 2023). "Patients with IBD and cancer history were exposed to anti-TNF inhibitors, vedolizumab and ustekinumab were tested and there was no increase in recurrent risk for cancer in either vedolizumab and ustekinumab after adjusting for age, IBD subtype, smoking, cancer stage." (PMID 37954750, 2023). "The role of tumor necrosis factor-alpha (TNF-α) in cancer has been known for many years." (PMID 37958406, 2023). "Hence, the correlation between TMMV and established predictive biomarkers of cancer cachexia, including IL-1, TNF-alpha, IL-6, CRP, and serum albumin, warrants investigation." (PMID 37959329, 2023).
cancer (continued). "Finally, our data show that Pol III inhibition is associated with lower NF-κB activation upon TNFα treatment, thus potentially suggesting the mechanism of Pol III inhibition-driven sensitisation of cancer cells to this cytokine." (PMID 36900285, 2023). "This is because adipose, considered as an active endocrine organ, can secrete various adipokines and interleukins, such as adiponectin and TNF‐α, which may drive chronic inflammation and the subsequent development of cancer." (PMID 37548289, 2023). "TNF-α and IL-2 have been shown to participate in both initiation and progression of cancer." (PMID 37296375, 2023). "Although these kinds of Th1 cytokines, including IL-12, TNF-α, and IFN-γ, are promising in cancer immunotherapy, their clinical application is associated with short half-life, narrow therapeutic window, severe dose-limiting toxicities, and difficulties in large-scale manufacturing." (PMID 38259474, 2023). "In all cases, the recombinant HDGF and TNFα were inhibitory to the growth of 3-D cancer organoids." (PMID 37047540, 2023). "This inflammatory state is frequently observed in cancer settings, particularly at the initiation of radiotherapy, triggering an overproduction of inflammatory cytokines such as interleukin-1, interleukin-6, and tumor necrosis factor-alpha." (PMID 37732299, 2023). "TIF1-γ mutation or overexpression in cancer cells was hypothesized activate CCL2 and TNF-α expression." (PMID 36357631, 2023). "However, the purified activity referred to as TNF was only capable of inducing necrosis in select cancers, especially in sarcomas, and this activity remained the exception rather than rule." (PMID 36195672, 2023). "Moreover, cancer related pathways, such as TNF signaling and NF-kappa B signaling, were also enriched." (PMID 38136595, 2023). "This may suggest that TNF has different roles in the colon during cancer, when compared with the small intestine during homeostasis." (PMID 37643009, 2023). "As a major mediator of inflammation-induced cancer, TNF plays an important role." (PMID 37764733, 2023). "When nigericin was combined with PD-1 antibody, T cells could secrete even higher TNF-α, suggesting the synergistic effect of nigericin with PD-1 on immune response of cancer cells." (PMID 37370831, 2023). "However, the cytotoxic effects of TNFα are often circumvented via activation of the NFκB signaling pathway, which is a critical regulator of survival and therapeutic resistance in several cancers." (PMID 37055579, 2023). "We, therefore, sought to determine whether inhibition of RNA polymerase III (Pol III), which synthesises several essential components of the protein biosynthetic machinery, would affect the response of cancer cells to TNFα." (PMID 36900285, 2023). "Additionally, they produce NO and cytokines (interleukin-1β; IL-1β, interleukin-6; IL-6, interferon-γ; IFN-γ, and tumor necrosis factor-α; TNF-α), and these build up immune response and suppress the growth of cancer cells." (PMID 37107267, 2023). "The functions of TNF were associated with the different engagement of its two receptors, TNFR1 and TNFR2, which are differentially expressed on various cell types including cancer cells." (PMID 36672682, 2023). "Interestingly, this study claimed that TILs can hinder cancer progression through the secretion of TNF-alpha on tumoral cells." (PMID 38077386, 2023). "However, it is justified by different previous studies that NF-κB p65 (RelA) and TNFα are biologically plausible candidates and play an important role in inflammatory processes involved in various cancers, including GBM." (PMID 37892820, 2023). "Cancer-promoting cytokines like IL-6, IL-11, TNF-α, IL-1β, and IL-23 vary by tumor type and stage." (PMID 37229273, 2023). "We suggest that a confirmation of these TNF-α-mediated events in appropriate translational studies would support the strategy that targeting miR-21 in cancers such as CRC could offer novel therapeutic opportunities." (PMID 36765584, 2023).
cancer (continued). "Therefore, the role of midazolam in the TNF-α release and cancer progression is currently questionable and further investigations should be conducted." (PMID 36765695, 2023). "Finally, whilst TNFα has well-established roles in promoting or inhibiting tumorigenesis, the majority of existing trials to date focussed on enhancing TNFα signalling in cancer treatment." (PMID 37455828, 2023). "A marker of inflammation in cancer cells is the level of TNF-α released into the media." (PMID 37644076, 2023). "Of note, most patients discontinued anti-TNF therapy at cancer diagnosis." (PMID 36983432, 2023). "As a result, from recent progress in cancer research, there is an emerging number of endogenous substances associated with inflammation and cancer to choose between, e.g., NF-κB, IL-6, IFN-γ, TNF-α, enzyme indoleamine-2,3-dioxygenase (IDO), and BRAF gene mutations." (PMID 37631245, 2023). "For instance, vit-D3/VDR complexes were shown to impair and inhibit anti-cancer cytokine networks, which are responsible for the recognition and elimination of malignant cells, including tumor necrosis factor (TNF)/nuclear factor-ķB (NF-ķB) signaling systems." (PMID 37835527, 2023). "Furthermore, TNF-α exhibited the potential to enhance the effectiveness of cancer treatment drugs/chemotherapy by promoting increased blood vessel permeability." (PMID 37895833, 2023). "The immune pathway mediated by pro-inflammatory cytokines such as IL-6 and TNF-α interferes with the biological effects of the insulin receptor downstream signaling and results in IR, which is also found to be closely involved in cancer development." (PMID 36969019, 2023). "Also, there is evidence to suggest that, in the presence of CeNPs, T-cells can release more interleukin-2 (IL-2) and tumor necrosis factor-α (TNF-α), helping to provide more effective cancer therapy." (PMID 37896153, 2023). "In addition to its key role in inflammation, TNF-α can induce cancer cell apoptosis through the tumor necrosis factor receptor 1 (TNFR1) signaling pathway." (PMID 37375653, 2023). "Although these studies have reported an increased cancer risk in patients taking TNF-α blockers, no definitive conclusions can be drawn, as many studies have not confirmed this trend." (PMID 36836166, 2023). "Interestingly, we noticed that TNF-α levels were higher in the HCW cohort compared to cancer patients both after Ag1 (p < 0.001) and Ag2 (p < 0.001) stimulation." (PMID 37376576, 2023). "The relative risk of death following cancer associated with anti-TNF exposure was not significant (RR 1.1, 95% CI: 0.8–1.6)." (PMID 36983432, 2023). "There has been a lack of evidence to suggest an increased risk of cancer among patients who receive TNF-i therapy, both in our study cohort and in the literature." (PMID 36624408, 2023). "In contrast, transfer of cancer-derived microparticles to monocytes was found to change their cytokine profile towards a reduced release of the pro-inflammatory cytokines GM-CSF and TNF-α and an increased release of the anti-inflammatory cytokine IL-1010." (PMID 37173330, 2023). "Similarly, in cancer survivors, tested 6 months to 5 years after the end of the treatment, we found that (in addition to V ̇O2peak, TNF-α, age) fatigability explained 35% of the variance in cancer-related fatigue severity." (PMID 37065809, 2023). "In summary, whether opioids possess an immunomodulatory capability and whether different types of opioids exert distinct effects on the release of TNF-α and subsequent cancer outcomes have been inconclusive thus far." (PMID 36765695, 2023). "In addition, the anti-TIF1-γ antibody and TNF-α combination depicted a high AUC for cancer existence in anti-TIF1-γ antibody-positive DM patients." (PMID 36357631, 2023). "We, therefore, hypothesized that HDAC inhibitors sensitize cancer cells to SMAC mimetics by enhancing TNF-α production via SP3." (PMID 36831656, 2023).
cancer (continued). "Of great interest in cancer therapy, Clostridia strains can be engineered to express cell suicide genes – such as bacterial enzyme cytosine deaminase - or eukaryotic host molecules like TNF-α." (PMID 37588093, 2023). "Additionally, cancer cells can also use the integrin/paxillin control mechanism to release tumor necrosis factor-α (TNFα)-converting enzyme-containing vesicles to improve their own growth microenvironment." (PMID 37175948, 2023). "Inhibition of the TNF-α/NF-κB axis by miRNAs may attenuate the invasive potential of cancer cells, as shown in colorectal cancer." (PMID 37233761, 2023). "IL4I1 is expressed by cancer cells in response to IFNγ and TNF-α." (PMID 36834576, 2023). "KEGG analysis was applied to enrich the related signaling pathways (p < 0.05), melanogenesis, cell adhesion molecules (CAMs), TNF signaling pathway, pathways in cancer tyrosine metabolism, gap junction, MAPK pathway, steroid biosynthesis, and cytokine-cytokine receptor interaction were dominant." (PMID 36969816, 2023). "The precise roles of mast cells and TNF-α in IBDs and colitis-associated cancer have not been fully elucidated." (PMID 37185713, 2023). "Finally, the regulatory axis of Iso2/TNF/T cell proliferation was demonstrated by in vitro and in vivo experiments and was observed in other cancers." (PMID 37047287, 2023). "Indeed, the cancer-related inflammation is promoted by TNFα secreted by TAMs that induces constitutive activation of NF-κB in tumor cells, which promotes their survival and invasion." (PMID 37284199, 2023). "IL-2, TNF-α, and NO were used as markers for cancer prevention." (PMID 37296375, 2023). "Plasma TNF-α levels higher than 28.37 pg/mL could identify cancer in anti-TIF1-γ antibody-positive DM patients." (PMID 36357631, 2023). "Thus, the upregulation of aromatase via the TNFα signaling pathway promotes the growth of cancer cells." (PMID 37869088, 2023). "During chronic inflammation, the repeated cycle of damage and healing of the intestinal epithelium with low TNF-α levels affects both cancer and immune cells and may keep the inflammation going, while preventing the death of transformed cells." (PMID 37555952, 2023). "In the pathway analysis, we found that PANoptosis score was positively correlated with IL6-JAK-STAT3 signaling, interferon-gamma response, inflammatory response, IL2-STAT5 signaling, and TNF-a signaling via the NF-kB signaling pathway in 33 diverse cancer types." (PMID 36890219, 2023). "Therefore, further in-depth experimental research and high-quality clinical trials are needed to explore the detailed molecular mechanisms involved in the relationship between anesthesia, TNF-α release, and cancer progression." (PMID 36765695, 2023). "The KEGG enrichment results suggested that these pathways, including the TNF signaling pathway, focal adhesion, proteoglycans in cancer, and leukocyte transendothelial migration, might play important roles in LUSC." (PMID 38259849, 2023). "Thus, although propofol anesthesia is recommended as a better choice for cancer surgery, prospective randomized control trials are needed to clarify its influence on the TNF-α release and cancer outcomes in the future." (PMID 36765695, 2023). "In addition, compared to AC cancer cells, MC cancer cells exhibited specific enrichment of certain signalling pathways, including the TNFα via NF-kB and oestrogen response early signalling pathways." (PMID 36690709, 2023). "When comparing the candidates to the non-candidate genes (those non-NFκB/TNF hallmark genes receiving no votes across all cancer types), the candidates displayed higher similarity to the canonical pathway genes TNF, RELA, NFKB1, and RELB." (PMID 37475016, 2023). "TNF-α, a versatile cytokine, plays a crucial role in treating local inflammation and cancer." (PMID 37958581, 2023). "Inflammatory cells release TNF, a cytokine that promotes inflammation and may contribute to cancer development." (PMID 36874133, 2023).